TTC23 (tetratricopeptide repeat domain 23)
Description:
Participates positively in the ciliary Hedgehog (Hh) signaling.
Synonyms: HCC-8; FLJ12572
Tractability: No criterion of Open Targets' tractability assessment is met for any kind of drug.
Gene: Protein-coding gene on chromosome 15 (99,136,323 to 99,251,226, reverse strand). Ensembl gene ENSG00000103852.
Subcellular location: Cell projection, cilium
Subcellular location (Human Protein Atlas): Cytosol; Primary cilium transition zone
Gene Ontology:
Molecular function: protein binding
Biological process: positive regulation of smoothened signaling pathway
Cellular component: cilium
Genetic constraint (gnomAD): Loss-of-function variants: 58 observed, 56.77 expected, observed/expected ratio (o/e) 1.02, 90% interval 0.83 to 1.27. The upper end of that interval is the gene's LOEUF score, 1.27, which puts it in group 5 of 6, group 1 being the genes least tolerant of losing a copy. Missense variants: 516 observed, 560.14 expected, observed/expected ratio (o/e) 0.92, 90% interval 0.86 to 0.99. Synonymous variants: 203 observed, 209.04 expected, observed/expected ratio (o/e) 0.97, 90% interval 0.87 to 1.09.
Homologues: Orthologues: chimpanzee TTC23 (98% identical), macaque TTC23 (95% identical), dog TTC23 (81% identical), pig TTC23 (76% identical), guinea pig TTC23 (75% identical), mouse Ttc23 (74% identical), rabbit TTC23 (72% identical), rat Ttc23 (72% identical), zebrafish ttc23 (34% identical). Paralogues in human: TTC23L (23% identical).
Diseases named in the same sentence as TTC23 in open-access papers:
TTC23 is named in the same sentence as 4 diseases in open-access papers, as found by Europe PMC text mining. Sharing a sentence is not in itself a finding about the gene and the disease. The quoted sentences say what the papers report.
breast carcinoma (1 paper, 2025). "Except for ATOH8, DNASE2, and TTC23, the involvement of the other nine co-expressed genes has been reported in breast cancer." (PMID 40282270, 2025). "Given the challenges associated with experimental studies on TTC23, we deemed it necessary to further elucidate the biological functions of DNASE2 and ATOH8 in the context of breast cancer." (PMID 40282270, 2025). "In contrast, the expression levels of PIK3R1, PNPLA2, ATOH8, TTC23, and CWF19L2 were dramatically lower in breast cancer samples than in healthy controls (p < 0.05)." (PMID 40282270, 2025). "Given the challenges associated with experimental studies on TTC23, we have decided to further investigate the biological functions of two genes, ATOH8 and DNASE2, which have not been extensively studied in breast cancer." (PMID 40282270, 2025).
cancer (2 papers, 2018 to 2026). A tumor composed of atypical neoplastic, often pleomorphic cells that invade other tissues. "TTC23-associated pathway activity, oncogenic state features, and immune contexture were characterized using expression stratification, enrichment and state scoring, cancer-immunity cycle analysis, and immune infiltration estimation." (PMID 42158948, 2026).
TTC23 also shares sentences with these, for which no sentence is quoted: glioblastoma (1 paper); tumor (1).